BRAF (B-Raf proto-oncogene, serine/threonine kinase)
Diseases named in the same sentence as BRAF in open-access papers (continued):
Sharing a sentence is not in itself a finding about the gene and the disease.
melanoma (continued). "An example of this is the acquired resistance of BRAFV600E-mutant melanoma cells to BRAF inhibitors that occurs as a result of MAPK pathway activation." (PMID 31640753, 2019). "In this study, we used computational predictions based on gene expression analyses to identify potential drugs against BRAF-mutant melanoma brain metastases." (PMID 30971321, 2019). "As for inter-tumor heterogeneity (heterogeneity among different melanoma sites in a patient), many researchers have mentioned the discrepancy of BRAF status between primary–metastatic and metastatic–metastatic melanoma." (PMID 31817947, 2019). "Effective treatment options are urgently needed for patients with BRAF-wt melanoma, particularly those with rapidly progressive disease." (PMID 30428063, 2019). "In this paper we focus on the involvement of activation of ErbB3 receptor following early exposure of melanoma cells to BRAF or MEK inhibitors, and the following induction of PI3K/AKT pathway." (PMID 31557826, 2019). "We advised future studies to evaluate the beneficial effects of anti-BRAF V600E target therapy on the Iranian melanoma patient who harbors this marker by way of immunostaining tumor tissue." (PMID 31531096, 2019). "Our model of acidic cells was represented by transient (24 hours) and chronic (three months)-adapted murine sarcoma viral oncogene homolog B (BRAF) melanoma cells to mimic short and long exposure of cancer cells to low pH." (PMID 31275384, 2019). "Significant improvements have extended the therapeutic options for treating brain metastases from melanoma, by combining potent BRAF inhibitors with checkpoint inhibitors or stereotactic surgery." (PMID 31481958, 2019). "The beneficial effects of combining Chk and Wee1 inhibitors have been demonstrated in BRAF mutant and wild-type melanoma cells, as well as in other human tumor cell lines." (PMID 30728057, 2019). "In another report, panobinostat recovered the anti-melanoma effects of encorafenib in BRAF inhibitor-resistant melanoma cell lines by the induction of caspase-dependent apoptotic cell death in human melanoma cell lines." (PMID 31514399, 2019). "BRAF alterations are known to commonly occur in other neural-crest derived tumors, including melanoma, and in high-grade neuroendocrine cancers." (PMID 31158244, 2019). "CD8 T-cells suppress resistance development to MAPK inhibitors in BRAF and NRAS-mutant melanoma with high mutational burden and targeting IPRES can enhance the anti-tumor activity of combined BRAF inhibitor and anti-PD-1 antibody." (PMID 31416487, 2019). "Vemurafenib and trametinib are the first BRAF and MEK inhibitors respectively to be approved for BRAF-mutated cancer (melanoma)." (PMID 30899200, 2019). "Trametinib (Novartis) is the first of this class to gain FDA approval, either as a single agent or in combination with a RAF inhibitor for BRAF V600 mutant melanoma." (PMID 31158244, 2019). "The activating BRAF missense mutation V600E is part of the MAPK pathway and occurs in 59% of melanoma patients and in at least 10% of CRC being a powerful prognostic factor." (PMID 31861874, 2019). "Half of all melanoma patients carry activating mutations in proto-oncogene v-Raf murine sarcoma viral oncogene homolog B (BRAF) that cause constitutive mitogen-activated protein kinase (MAPK) signaling and subsequently, unrestricted melanoma growth." (PMID 30745871, 2019). "Mouse melanoma cell cultures with RAC1P29S showed lower levels of apoptosis when exposed to a BRAF inhibitor, supporting the idea that the resistance to therapy observed in our mouse model resulted from RAC1P29S-mediated suppression of apoptosis." (PMID 31257073, 2019).
melanoma (continued). "Vemurafenib and dabrafenib, selective BRAF-mutant inhibitors, were approved by the FDA for the treatment of melanomas carrying the most common activating mutation BRAFV600E." (PMID 31181622, 2019). "In 2011, a Phase III clinical trial for vemurafenib was conducted in BRAF-V600E melanoma patients with metastatic disease." (PMID 31672130, 2019). "By contrast, the activation of autophagic/lysosomal pathways can occur as the consequence of anticancer therapies, as has been demonstrated in melanoma treated with anti-BRAF targeted agents." (PMID 31355143, 2019). "Nevertheless, transcriptional re-wiring of c-MYC has recently been described in BRAF-inhibitor resistant melanoma sensitizing to bromodomain inhibition." (PMID 30651597, 2019). "Combination therapy with BRAFi and MEKi has remarkably improved survival in the adjuvant setting for patients with BRAF mutant melanomas, and combining a BRAFi and an EGFRi has improved tumor regression in BRAF mutant colorectal cancer xenografts." (PMID 30636931, 2019). "When subjected to multivariate analysis with clinically known prognostic markers of melanoma (Breslow thickness, ulceration, dermal mitosis level), BRAF remained as a significant independent prognostic factor for SNB positivity." (PMID 31039200, 2019). "Collectively, these results indicate that prolonged MEKi in BRAF‐mutant melanoma cells induces CD271 and AMPK phosphorylation, while also increasing autophagy and disrupting cellular energy production." (PMID 30339727, 2019). "BRAF is a driver oncogene in various human cancers including melanoma, and was the first described oncoprotein with serine/threonine kinase activity." (PMID 31578454, 2019). "Improved understanding of the genetic landscape of melanoma led to the development of BRAF and MEK inhibitors for patients with BRAF mutated tumors." (PMID 31671846, 2019). "Combined use of BRAF and MEK inhibitors is one of the standards of care for patients with advanced BRAF-mutant melanoma." (PMID 30675668, 2019). "Several other studies using melanoma cell lines found augmented anti-tumor immune responses under BRAF inhibition." (PMID 31747929, 2019). "The molecular basis of vemurafenib resistance has been extensively investigated in recent years in patients with BRAF mutant solid organ malignancies such as melanoma and colorectal cancer." (PMID 30341394, 2019). "The high rate of both response and resistance development of BRAF-mutant melanoma patients to BRAF inhibitor (BRAFi) treatment has made such cell lines important models for understanding challenges associated with targeted inhibitors." (PMID 31166947, 2019). "Another paradigmatic example is the initial good response to specific inhibitors in melanomas harboring the BRAFV600E mutation, compared to the protumor effect of the same inhibitors in colon adenocarcinomas carrying similar BRAF mutations." (PMID 31001323, 2019). "The introduction of BRAFi/MEKi combination regimens has proven to be a critical therapeutic breakthrough in the treatment of BRAF-mutant melanoma." (PMID 31653096, 2019). "Multiple complex and context-dependent mechanisms confer resistance to the BRAF inhibitor in melanoma." (PMID 31126017, 2019). "Enrichment of shRNA at day 14 compared to day 0 indicated that it targeted an anti-growth gene, while depletion of a shRNA suggested it targeted a pro-growth gene (e.g., shRNAs targeting BRAF in melanoma)." (PMID 31110180, 2019). "A combination of BRAF and MEK1/2 inhibition can overcome acquired resistance with improved response rates and patient progression-free survival in melanoma BRAFV600E patients compared to BRAF monotherapy." (PMID 31083627, 2019). "The FDA approved vemurafenib for the treatment of patients with mutant-V600E BRAF metastatic melanomas in 2011." (PMID 30975211, 2019).
melanoma (continued). "To demonstrate the potential of our technology to shed light on such mechanisms, we next probed kinase activation upon acquired BRAF inhibitor (BRAFi) resistance in melanoma." (PMID 31521607, 2019). "Several studies showed expression of inhibitory ligand PD-L1 was dramatically increased with treatment of BRAF inhibitors in melanoma cell lines and patient-derived biopsies with metastatic melanoma." (PMID 31134073, 2019). "In contrast, no distinct differences were observed for activation of S6 and ERK indicating activation of the respective pathways by alternative mechanisms in the BRAF wild-type models, an effect which has previously been described in both glioma and melanoma." (PMID 31391125, 2019). "Sunitinib can be used for treatment of patients with BRAF wild-type melanoma, but is relatively ineffective, thus strategies to increase its effectiveness would improve treatment of approximately half of melanoma patients who lack BRAF mutations." (PMID 31615091, 2019). "The melanoma patients were treated per standard of care with anti-PD-1 based regimen as either a first line or salvage therapy after progression on ipilimumab or BRAF inhibitors." (PMID 30992053, 2019). "Trametinib is approved by the FDA as a single drug or combined with dabrafenib for the treatment of incurable BRAF mutant melanoma." (PMID 31428570, 2019). "MITF is essential for melanoma cells and we discovered that BRAF employs a PAX3/BRN2 rheostat to regulate MITF expression." (PMID 30277012, 2019). "The relationship between senescence signalling and BRAF inhibitor resistance is best exemplified in melanoma where drug resistance is also typically accompanied by dedifferentiation markers such as NGFR, which is inducible by type II interferons (IFNγ)." (PMID 30850015, 2019). "Conversely, we observed minimal change in MCL-1 dependence in cells derived from a patient with a BRAF-mutant melanoma who had developed resistance to BRAF/MEK inhibitors." (PMID 31727958, 2019). "In the present investigation, we explored the possibility to interfere with oncogenic signaling pathways in BRAF-mutant melanoma cells through NDI-based G4 ligands." (PMID 31635389, 2019). "Thereafter, our laboratory demonstrated that Ole enhances chemotherapy of BRAF melanoma cells, by downregulating the pAKT/pS6 pathway." (PMID 31766676, 2019). "As the selective inhibitor of BRAF kinase, vemurafenib exhibits effective antitumor activities in patients with V600 BRAF mutant melanomas." (PMID 30717768, 2019). "These drugs improve the outcome of patients with advanced BRAF V600‐mutant melanoma, with a high rate of tumor response and improvement in progression‐free survival and overall survival compared with standard cytotoxic chemotherapy." (PMID 30499222, 2019). "In BRAF-mutant melanoma cells, BRN2 transcriptionally represses the expression of PDE5A (cyclic nucleotide phosphodiesterase 5A), leading to increased cGMP levels and phosphorylation of MYL2 (myosin light chain 2) and consequently increased invasion." (PMID 30866509, 2019). "The current development of BRAF inhibitors has revolutionized the treatment of unresectable melanoma." (PMID 31817947, 2019). "For melanoma, multiple targeted drugs (BRAF/MEK inhibitors) have been approved in recent years and extended survival for patients with BRAFV600E/K mutations." (PMID 31253656, 2019). "A final ctDNA assessment at week 119, revealed that BRAF V600R ctDNA continues to be undetectable which is consistent with sustained complete response of melanoma." (PMID 31727009, 2019). "We have screened a 274-compound kinase inhibitor library in 3 BRAF mutant melanoma cell lines (each one sensitive or made resistant to 2 distinct BRAFi)." (PMID 30728057, 2019).
melanoma (continued). "We explored the TWIST1-regulated transcriptome through expression array analysis using invasive mutant BRAF melanoma cells as a model." (PMID 30911007, 2019). "In our study, BRAF V600E mutation was associated with adverse RFS and OS in the superficially spreading melanomas, the histological subtype which typically harbors BRAF mutations." (PMID 31039200, 2019). "Mechanistic investigations showed that 2155–14 induces ER stress leading to potentiation of basal autophagy resulting in melanoma cell death in BRAF and NRAS mutated melanoma cells." (PMID 31573152, 2019). "We present experimental evidence for the top drug combination predicted by our method for BRAF-mutant melanoma and validate gene expression at the network level and for highly ranked centrality genes." (PMID 30820351, 2019). "Among these, activating mutations in BRAF and NRAS gene and inactivating mutations in NF1 gene accounts for over 80% of melanoma and results in the activation of MAP kinase pathway." (PMID 31217906, 2019). "NAMPT induces melanoma cell proliferation accompanied by a phenotypic switch towards an invasive phenotype and resistance to BRAF inhibitors." (PMID 31569642, 2019). "Preclinical data showed an increase in CD8+ T-cell recognition of tumor cells by inducing rapid upregulation of MHC class I surface expression in BRAF-mutant melanoma cells." (PMID 31817189, 2019). "Of these, 360 BRAF-mutant advanced melanoma patients with a baseline serum LDH of ≥2× ULN received first-line targeted therapy and were included for analyses." (PMID 31817189, 2019). "Despite the failures in the non-melanoma BRAF-V600E basket trial for vemurafenib, the existing FDA requirement and warning for BRAF mutation status provide a translational structure that cannot be ignored." (PMID 31672130, 2019). "Survival predictions are currently determined on the basis of NRAS/BRAF mutations, even though TERT promoter mutations have been recently associated with a poor prognosis in stage I-II melanomas." (PMID 30934988, 2019). "In this study, we used a BRAF(V600E) mutant melanoma cell line as a model system to evaluate genome-wide changes in gene expression, enhancer chromatin marks, and transcription factor occupancy in response to the MEK inhibitor AZD6244." (PMID 31399133, 2019). "The therapeutic landscape of advanced melanoma has dramatically shifted from cytotoxic drugs to BRAF-/ MEK-targeted agents and, recently, PD1 inhibitors, resulting in a durable response and prolonged survival." (PMID 31796647, 2019). "Compound 2155–14 induces ER stress leading to the potentiation of basal autophagy and melanoma cell death in BRAF and NRAS mutated melanoma cells indicating that this can be a novel approach to a much-needed broad-spectrum melanoma therapy." (PMID 31573152, 2019). "In our previous study, we showed that in BRAF melanoma cells, Ole affected cell proliferation by downregulation of the pAKT/pS6 pathway." (PMID 31766676, 2019). "Recent studies demonstrated that treating BRAF-mutant melanoma cells with BRAF inhibitors leads to significantly upregulated expression of MDAs such as MART-1, gp-100, Trp-1, and Trp-2." (PMID 31134073, 2019). "The first targeted therapy to be introduced was monotherapy with BRAF inhibitors such as vemurafenib or dabrafenib for the treatment of advanced BRAF‐mutant melanoma (Martin‐Liberal and Larkin, 2015)." (PMID 30499222, 2019). "In conclusion, we here leveraged robust in vivo model systems of brain metastasis to demonstrate the effects of β-sitosterol on BRAF-mutant melanoma." (PMID 30971321, 2019). "Further specific BRAF inhibitors have gained approval for treatment of BRAF-mutant melanoma such as dabrafenib and encorafenib." (PMID 30987166, 2019). "A commercial kinase inhibitor library of 274 compounds was tested on 3 different BRAF mutant melanoma cell lines, A375, IGR37 and 501Mel." (PMID 30728057, 2019).
melanoma (continued). "For example, co-treatment with MEK inhibitors partly reversed the expression of PD-L1, due to an increased MAPK signaling, which characterizes melanoma cell lines with acquired resistance to BRAF inhibitors." (PMID 31762942, 2019). "Amplification of MITF, a melanoma lineage-specific transcription factor, was shown to promote acquired resistance to BRAF inhibition." (PMID 31426419, 2019). "Resistance to BRAF kinase inhibitors is important for the long-term treatment of advanced melanoma in the real world." (PMID 31514399, 2019). "Ferroptosis induction and execution were evaluated in metastasis-derived wild-type and oncogenic BRAF melanoma cells, and the process responsible for the resistance has been dissected at molecular level." (PMID 31780644, 2019). "In pre-clinical BRAF-wt melanoma models, co-administering a taxane and a MEK inhibitor substantially induces tumour regression and apoptosis." (PMID 30428063, 2019). "In this context, activation of MAPK or PI3K/AKT signaling pathways contributes to the relapse of melanoma patients treated with BRAF inhibitors." (PMID 31635389, 2019). "Based on the findings that MAPK pathway is activated in a large percentage of melanoma, clinically effective BRAF kinase and MEK1/2 kinase inhibitors have been developed and are being used to treat metastatic melanoma patients with BRAF mutations." (PMID 31217906, 2019). "BRAF inhibitors (e.g. vemurafenib, dabrafenib) combined with MEK inhibitor (e.g. trametinib) effectively attack BRAFV600E-mutated melanomas." (PMID 30900145, 2019). "Recent clinical trials results showed significantly increased progression free survival and overall survival in BRAF- mutant metastatic melanomas with dual BRAF and MEK inhibitors compared to BRAF inhibitor monotherapy." (PMID 31672130, 2019). "Systemic treatment of melanoma, has recently undergone revolutionary changes with the discovery of predictive tumor biomarkers, such as BRAF, which predict the efficacy of targeted therapy with small molecule inhibitors such as vemurafinib, or dabrafenib." (PMID 30735560, 2019). "We performed a meta-analysis of CVAEs for patients with melanoma being treated with BRAF and MEK inhibitors using data from 5 RCTs with 2317 participants." (PMID 31397860, 2019). "BRAF/MEK inhibitors, such as vemurafenib/cobimetinib and dabrafenib/trametinib, target melanoma cells with oncogenic BRAF mutations, including BRAFV600E and BRAFV600K." (PMID 31817947, 2019). "Low levels of KIT expression have been widely described in most cases of cutaneous melanoma, especially in BRAFV600mut melanoma, due to the endogenous activation of MAPK activation by BRAF mutations." (PMID 31426590, 2019). "This was followed by a multicenter, open-label, phase II 22 trial (COMBI-MB) that examined intracranial response to combination dabrafenib-trametinib in 23 patients with BRAF-mutant melanoma BM." (PMID 31803366, 2019). "Current standard therapies for melanoma include treatments with checkpoint blockades or with vemurafenib and dabrafenib, small molecule inhibitors for BRAF and MEK." (PMID 31040916, 2019). "In our study, human melanoma cells with BRAFV600E mutation were treated with chemotherapeutics and a BRAF inhibitor." (PMID 30631106, 2019). "Both pazopanib and trametinib can safely be given with weekly paclitaxel chemotherapy at the full monotherapy dose and showed promising activity in BRAF-wt melanoma in early clinical studies." (PMID 30428063, 2019). "Using a highly characterized metastatic BRAF-mutant human melanoma xenograft model, we isolated and sorted tumor cells from brain, bone, adrenals and ovaries by flow cytometry." (PMID 30971321, 2019). "Concentrations down to 30 μmol L−1 magnolol‐induced apoptosis and cell death in NRAS‐ and BRAF‐mutant melanoma cells, whereas BRAF/NRAS wild‐type melanoma cells were only susceptible at higher concentrations (80 μmol L−1)." (PMID 30793515, 2019).